SGF29 (SAGA complex associated factor 29)
Description:
Chromatin reader component of some histone acetyltransferase (HAT) SAGA-type complexes like the TFTC-HAT, ATAC or STAGA complexes. SGF29 specifically recognizes and binds methylated 'Lys-4' of histone H3 (H3K4me), with a preference for trimethylated form (H3K4me3). In the SAGA-type complexes, SGF29 is required to recruit complexes to H3K4me. Involved in the response to endoplasmic reticulum (ER) stress by recruiting the SAGA complex to H3K4me, thereby promoting histone H3 acetylation and cell survival. Also binds non-histone proteins that are methylated on Lys residues: specifically recognizes and binds CGAS monomethylated on 'Lys-506' (By similarity).
Synonyms: CCDC101; FLJ32446; TDRD29; STAF36
Tractability: Small molecule: it has a high-quality binding pocket. PROTAC: ubiquitination databases record sites on it; its protein half-life has been measured.
Target class: Methyl-lysine/arginine binding protein; Reader; Epigenetic regulator; Tudor domain
Gene: Protein-coding gene on chromosome 16 (28,553,915 to 28,591,790, forward strand). Ensembl gene ENSG00000176476.
Subcellular location: Nucleus
Subcellular location (Human Protein Atlas): Nucleoli; Nucleoplasm
Pathways (Reactome):
Chromatin organization: HATs acetylate histones
Gene expression (Transcription): Formation of WDR5-containing histone-modifying complexes
Gene Ontology:
Molecular function: histone H3K36me3 reader activity; histone H3K4me3 reader activity; protein binding; methylation-dependent protein binding
Biological process: negative regulation of transcription by RNA polymerase II; regulation of cell cycle; regulation of cell division; regulation of DNA-templated transcription; regulation of transcription by RNA polymerase II; regulation of tubulin deacetylation; response to endoplasmic reticulum stress; transcription initiation-coupled chromatin remodeling; establishment of protein localization to chromatin; positive regulation of DNA-templated transcription; regulation of DNA repair; regulation of embryonic development; regulation of RNA splicing
Cellular component: ATAC complex; nucleolus; nucleoplasm; SAGA-type complex; mitotic spindle; nucleus; SAGA complex
Genetic constraint (gnomAD): Loss-of-function variants: 15 observed, 39.72 expected, observed/expected ratio (o/e) 0.38, 90% interval 0.25 to 0.58. The upper end of that interval is the gene's LOEUF score, 0.58, which puts it in group 2 of 6, group 1 being the genes least tolerant of losing a copy. Missense variants: 184 observed, 406.89 expected, observed/expected ratio (o/e) 0.45, 90% interval 0.4 to 0.51. Synonymous variants: 151 observed, 166.53 expected, observed/expected ratio (o/e) 0.91, 90% interval 0.79 to 1.04.
Homologues: Orthologues: macaque SGF29 (99% identical), dog SGF29 (99% identical), rat Sgf29 (99% identical), mouse Sgf29 (98% identical), guinea pig SGF29 (98% identical), tropical clawed frog sgf29 (95% identical), zebrafish sgf29 (91% identical), pig SGF29 (88% identical), chimpanzee SGF29 (76% identical), Drosophila melanogaster Sgf29 (48% identical), Caenorhabditis elegans Y17G9B.8 (31% identical), Caenorhabditis elegans T22B7.4 (27% identical).
Diseases named in the same sentence as SGF29 in open-access papers:
SGF29 is named in the same sentence as 21 diseases in open-access papers, as found by Europe PMC text mining. Sharing a sentence is not in itself a finding about the gene and the disease. The quoted sentences say what the papers report.
AIDS (1 paper, 2022). A syndrome resulting from the acquired deficiency of cellular immunity caused by the human immunodeficiency virus (HIV). "Given the apparent association between the loss of Sgf29, virulence, and the presence of morphological variants, we extended our analysis to the clinical isolate set from our previous study on HIV/AIDS patients in Botswana." (PMID 35258331, 2022).
atopic asthma (1 paper, 2023). An asthma that is characterized by symptoms that are triggered by an allergic reaction caused by inhaled allergens such as dust mite allergen, pet dander, pollen and mold. "Notably, MSL1, MOCS2, NUPR1, and SGF29 interact with proteins encoded by three genes that are associated with post bronchodilator FEV1, atopic asthma and AD." (PMID 36574990, 2023).
Crohn disease (1 paper, 2024). A gastrointestinal disorder characterized by chronic inflammation involving all layers of the intestinal wall, noncaseating granulomas affecting the intestinal wall and regional lymph nodes, and transmural fibrosis. "Some of these traits (i.e., platelet-to-lymphocyte ratio, general cognitive ability) as well as Crohn’s disease are further linked to JIA through the neighbouring cluster 6 genes (HLA-FAS1, BAK1, CLN3, SGF29)." (PMID 39175752, 2024).
glioblastoma (1 paper, 2024). The most malignant astrocytic tumor (WHO grade IV). "Next, we examined the response of SGF29-dependent MV4-11 leukemia cells and the SGF29-independent U251 glioblastoma cells to these 190 candidate compounds (plus 15 reference compounds) using a CellTiter Glo screen." (PMID 38394203, 2024).
leukemia (1 paper, 2024). A malignant (clonal) hematologic disorder, involving hematopoietic stem cells and characterized by the presence of primitive or atypical myeloid or lymphoid cells in the bone marrow and the blood. "Treatment of Cpd_DC60 also suppressed the expression of RPL8 and RPS2, resembling the impact caused by SGF29 depletion in leukemia." (PMID 38394203, 2024). "We showed that depletion of Sgf29 delayed the leukemia development in the recipient mice with a decreased engraftment of CD45.2+ leukemic cells into peripheral blood and spleen of the recipient mice." (PMID 38394203, 2024). "First, we performed a high-density CRISPR gene tiling scan in MLL-AF9-Cas9+ leukemia using a pool of 147 sgRNAs that targeted every “NGG” protospacer adjacent motifs (PAMs) within the endogenous Sgf29 coding exons (targeting density of ~2.0 amino acids/sgRNA)." (PMID 38394203, 2024). "Our histone mass spectrometry revealed a precise elimination of H3K9ac by targeting a single gene SGF29, indicating the utility of SGF29 to serve as a selective and perhaps more effective target for H3K9ac blockade and leukemia therapy." (PMID 38394203, 2024). "Immunoblotting revealed a notable reduction of H3K9ac level only in the Cpd_DC60 treated leukemia cells, marking Cpd_DC60 as our leading SGF29 inhibitor." (PMID 38394203, 2024). "This pipeline allowed us to identify the first lead inhibitor targeting SGF29’s Tudor 2 domain, which has a selective efficacy against leukemias and other types of hematopoietic malignancies." (PMID 38394203, 2024). "On the bais of the local smoothen modeling of the normalized CRISPR score (NCS), our Sgf29 gene body scan revealed the dependency of leukemia cells to the C-terminal tandem Tudor domain (TTD) region of SGF29 (blue dashed box)." (PMID 38394203, 2024). "In consistence with this anti-leukemia phenotype, genetic depletion of SGF29 substantially delayed leukemia onset and prolonged the overall survival of leukemia mice (gray versus red)." (PMID 38394203, 2024). "S10), providing proof-of-concept evidence of therapeutic targeting SGF29 in vivo for leukemia treatment." (PMID 38394203, 2024). "Using this approach, we identified a lead inhibitor that selectively targets SGF29’s Tudor domain and demonstrates efficacy against leukemia." (PMID 38394203, 2024). "This “human-in-mouse” xenograft leukemia model revealed a notable reduction of the leukemia burden by SGF29 depletion (gray versus red)." (PMID 38394203, 2024). "CRISPR-SADD pipeline identifies SGF29 Tudor domain inhibitor for leukemia therapy." (PMID 38394203, 2024). "Notably, ectopic expression of RPL8 and RPS2 was insufficient to reverse the impact triggered by sgSGF29, suggesting additional factors downstream of SGF29 are likely required for leukemia maintenance." (PMID 38394203, 2024). "On the other hand, ectopic expression of the synthetic SGF29 cDNA completely reversed sgSGF29-dual–mediated anti-leukemia phenotypes (green group), providing proof-of-concept evidence of targeting SGF29 in vivo to disrupt the progression/maintenance of human leukemia." (PMID 38394203, 2024). "In summary, our study highlighted that SGF29-mediated H3K9 acetylation could serve as a leukemia-selective therapeutic target." (PMID 38394203, 2024). "To examine the selectivity of SGF29 inhibition against different blood cancer types, we performed Cpd_DC60 titration experiments in MLL-r leukemia (seven cell lines), non–MLL-r blood cancer (green; seven cell lines), and solid tumor (blue; three cell lines) cells." (PMID 38394203, 2024). "This CRISPR domain screen identified the second Tudor domain of SGF29 (SGF29_Tudor 2), a histone H3K4me3 binding protein in the SAGA and ATAC histone modification complexes, as the top essential Tudor domain in MLL-AF9 leukemia." (PMID 38394203, 2024). "Notably, the connection between SGF29 and leukemia progression (also SGF29 to ribosome) was not reported before." (PMID 38394203, 2024).
cancer (4 papers, 2021 to 2024). A tumor composed of atypical neoplastic, often pleomorphic cells that invade other tissues. "Among them, PRDM16, SETDB2, SGF29, and ZCWPW2 were protective genes and were all downregulated in the tumor samples, while the others were enriched in the cancer tissues and were associated with poor prognosis." (PMID 36263018, 2022). "Given the contradictory roles of SGF29 in cancers, it is worth initiating further studies." (PMID 36263018, 2022). "Thus, it remains to be determined whether the effects of SGF29 in ALT are direct, through recognition of telomeric chromatin, or indirect, via effects on gene expression, and whether targeting SGF29 could be effective or selective in ALT-positive cancers." (PMID 39605432, 2024).
tumor (4 papers, 2021 to 2025). "This raises the interesting possibility that either loss or overexpression of Sgf29 in tumour cells can act as a therapeutic biomarker for potential resistance to hydroxamates." (PMID 33721015, 2021). "Our research indicates SGF29 is measurable in serum when secreted as part of a malignant cellular process or when tumor cells die and release their contents into the bloodstream." (PMID 41463256, 2025). "As a number of tumour cells show increased levels of Sgf29 (COSMIC database COSU376, COSU377 and COSU414) we tested whether overexpression would also alter TSA sensitivity." (PMID 33721015, 2021). "We confirmed that SETDB2 (HR: 0.773, 95%CI: 0.640–0.932), SGF29 (HR: 0.918, 95%CI: 0.860–0.979), PRDM16 (HR: 0.891, 95%CI: 0.807–0.983), CBX7 (HR: 0.906, 95%CI: 0.833–0.986), and ZCWPW2 (HR: 0.325, 95%CI: 0.117–0.901) were protective genes, and they were all downregulated in the tumor samples." (PMID 36263018, 2022).
infection (1 paper, 2017). The state of being infected such as from the introduction of a foreign agent such as serum, vaccine, antigenic substance or organism. "Perhaps more importantly, this work suggests that inactivation–even temporarily–of Sgf29 could be a highly effective mechanism for C. neoformans to rapidly undergo heritable microevolutionary change without altering its genetic material, and enhance the success of infection." (PMID 29263343, 2017). "We are therefore unable to determine whether the patients were infected with a hypervirulent environmental strain lacking SGF29, or if the loss of SGF29 occurred early in infection as part of the microevolutionary burst this species is known to undertake during passage through the human host." (PMID 29263343, 2017).
SGF29 also shares sentences with these, for which no sentence is quoted: anemia (1 paper); asthma (1); autoimmune disease (1); blood cancer (1); diabetes (1); hematopoietic cancers (1); hepatocellular carcinoma (1); Hutchinson-Gilford progeria syndrome (1); inflammatory bowel disease (1); lung carcinoma (1); Obesity (1); stomach cancers (1); Werner syndrome (1).